PRIM1 (DNA primase subunit 1)
Description:
Catalytic subunit of the DNA primase complex and component of the DNA polymerase alpha complex (also known as the alpha DNA polymerase-primase complex - primosome/replisome) which play an essential role in the initiation of DNA synthesis. During the S phase of the cell cycle, the DNA polymerase alpha complex (composed of a catalytic subunit POLA1, an accessory subunit POLA2 and two primase subunits, the catalytic subunit PRIM1 and the regulatory subunit PRIM2) is recruited to DNA at the replicative forks via direct interactions with MCM10 and WDHD1 (By similarity). The primase subunit of the polymerase alpha complex initiates DNA synthesis by oligomerising short RNA primers on both leading and lagging strands. These primers are initially extended by the polymerase alpha catalytic subunit and subsequently transferred to polymerase delta and polymerase epsilon for processive synthesis on the lagging and leading strand, respectively (By similarity). In the primase complex, both subunits are necessary for the initial di-nucleotide formation, but the extension of the primer depends only on the catalytic subunit. Synthesizes 9-mer RNA primers (also known as the 'unit length' RNA primers). Incorporates only ribonucleotides in the presence of ribo- and deoxy-nucleotide triphosphates (rNTPs, dNTPs). Requires template thymine or cytidine to start the RNA primer synthesis, with an adenine or guanine at its 5'-end. Binds single stranded DNA (By similarity).
Synonyms: p49; PDIL
Tractability: Small molecule: an approved drug acts on it; a structure with a bound ligand is known. PROTAC: ubiquitination databases record sites on it; its protein half-life has been measured.
Gene: Protein-coding gene on chromosome 12 (56,730,438 to 56,752,374, reverse strand). Ensembl gene ENSG00000198056.
Pathways (Reactome):
DNA Replication: Activation of the pre-replicative complex; DNA replication initiation; Polymerase switching; Processive synthesis on the lagging strand; Removal of the Flap Intermediate
Cell Cycle: Inhibition of replication initiation of damaged DNA by RB1/E2F1; Polymerase switching on the C-strand of the telomere; Telomere C-strand synthesis initiation
Disease: Defective pyroptosis
Gene Ontology:
Molecular function: DNA-directed RNA polymerase activity; magnesium ion binding; protein binding; ribonucleotide binding; zinc ion binding
Biological process: DNA replication initiation; DNA replication, synthesis of primer
Cellular component: alpha DNA polymerase:primase complex; membrane; nucleoplasm
Genetic constraint (gnomAD): Loss-of-function variants: 19 observed, 33.82 expected, observed/expected ratio (o/e) 0.56, 90% interval 0.39 to 0.82. The upper end of that interval is the gene's LOEUF score, 0.82, which puts it in group 3 of 6, group 1 being the genes least tolerant of losing a copy. Missense variants: 265 observed, 326.31 expected, observed/expected ratio (o/e) 0.81, 90% interval 0.73 to 0.9. Synonymous variants: 109 observed, 100.18 expected, observed/expected ratio (o/e) 1.09, 90% interval 0.93 to 1.28.
Gene-disease validity (ClinGen):
ClinGen rates the evidence that PRIM1 causes each of these diseases.
primordial dwarfism-immunodeficiency-lipodystrophy syndrome (autosomal recessive): Moderate.
Homologues: Orthologues: chimpanzee PRIM1 (100% identical), macaque PRIM1 (99% identical), pig PRIM1 (94% identical), dog PRIM1 (92% identical), guinea pig PRIM1 (91% identical), mouse Prim1 (90% identical), rat Prim1 (89% identical), tropical clawed frog prim1 (70% identical), zebrafish prim1 (67% identical), Drosophila melanogaster Prim1 (41% identical), Caenorhabditis elegans pri-1 (37% identical), Caenorhabditis elegans T24C4.5 (27% identical).